CDKN2A (cyclin dependent kinase inhibitor 2A)
Diseases named in the same sentence as CDKN2A in open-access papers (continued):
Sharing a sentence is not in itself a finding about the gene and the disease.
tumor (continued). "In only 2 of these tumour sets did the grade of the tumour progress; in both cases from GII to GIII, both with normal copy number of p16/CDKN2A." (PMID 25432631, 2015). "The relative expression of the genes CDKN2A, CDKN2B, and RB1 was significantly decreased in all the examined tumor grades." (PMID 26317630, 2015). "By normalizing to this control locus, we determined genomic copy number estimates of CDKN2A and IKZF1 in tumor DNA samples." (PMID 26575185, 2015). "GISTIC analysis defined significant common regions of amplification and deletion that harbour multiple oncogenes (for example, MYC and CCND1) and tumour suppressors (for example, SMAD4 and CDKN2A)." (PMID 25855536, 2015). "These genes are localised close to known cyclin-dependent kinase inhibitors and tumour suppressors CDKN1C and CDKN2A/B, respectively, but both FAF1 and MTAP have recently been proposed to harbour tumour suppressor activity in their own right." (PMID 24548782, 2014). "Genes such as RASSF1A, CDKN2A and CCNA1 were successfully validated to be highly methylated in cancer tissue compared to adjacent non-tumor and normal liver tissues." (PMID 24635883, 2014). "This became the first model of EP, accurately recapitulating the tumor histology and gene expression profiles of the EPHB2/CDKN2A subgroup." (PMID 25008045, 2014). "Some of the mutations identified in this study are in genes well-known for their role as tumor suppressors, such as PTEN and CDKN2A." (PMID 24983247, 2014). "This independent series comprised 33 GBMs from the Salpêtrière database treated with the combination of bevacizumab/irinotecan at recurrence and for whom the CDKN2A locus homozygous deletion and EGFR amplification status were available in the initial tumor." (PMID 24804210, 2014). "In the same LD block with this gene are CDKN2A (P16), CDKN2B (P15) and ARF (P14), which are all recognized tumour suppressor genes." (PMID 24676469, 2014). "Frequently methylated genes in HCC such as P16/CDKN2A, CDH1 and GSTP1 were also found to be similarly hypermethylated in our tumor samples." (PMID 25093504, 2014). "CDKN2A/ARF and CDKN2B are known tumor suppressors and have well-established roles in cell proliferation, apoptosis, senescence and aging." (PMID 23306151, 2013). "Several genes displayed correlations between epigenetic modification and clinically relevant parameters, including invasiveness (CDKN2A; DAPK; Rb1), sex (MAGE-A3), tumor size (GNAS1), and histopathological subtype (CDKN2A; MEG3; p27; RASSF1A; Rb1)." (PMID 24367530, 2013). "CDKN2A/ARF and CDKN2B are three tumour suppressor genes which play a central role in cell cycle inhibition, senescence and stress-induced apoptosis." (PMID 23101500, 2012). "Known tumor suppressor genes, e.g., CDKN2A (9p21.3), PTEN (10q23), and RB1 (13q14) were located within HD regions, as well as genes with potential tumor suppressor properties, e.g., CUL3 (2q36.2) and MGMT (10q26)." (PMID 22685613, 2012). "Two important tumor suppressor loci map 9p21: CDKN2B (p15INK4B) and CDKN2A, which code for two alternative protein products, p14ARF and p16INK4A." (PMID 22389839, 2012). "ln the case of CDKN2A, where a certain degree of age-related methylation in normal colonic mucosa may occur, the quantitative nature of the pyrosequencing method allows one to account for background methylation to provide a more accurate assessment of tumor-specific hypermethylation." (PMID 22925370, 2012).
tumor (continued). "Whole genome shotgun sequencing detected the rearrangements involving several known tumor suppressors in 20 tumor/normal sample pairs, which were further confirmed by RNA sequencing including PTEN, RB1, NOTCH1, NF1, and CDKN2A." (PMID 23109866, 2012). "We report here that the CCND1/CDKN2A mRNA expression ratio predicts the RB1 status of cell lines in vitro and xenograft tumors and clinical tumor samples in vivo." (PMID 21447152, 2011). "The present study identified that the expression ratio of CCND1/CDKN2A predicts the status of RB1 in both cultured cancer cell lines and clinical tumor samples." (PMID 21447152, 2011). "The losses encompassed the tumor suppressor genes CDKN2A and CDKN2B, which are frequently deleted in many tumor types." (PMID 22613809, 2011). "DNA methylation at the promoter region of the MGMT, CDKN2A, SFRP1, TMEFF2, HS3ST2 (3OST2), RASSF1A and GATA4 genes was evaluated by quantitative methylation specific PCR in both tumor and corresponding normal appearing colorectal mucosa samples." (PMID 20098741, 2010). "The eight genes displaying variable DNA methylation patterns in a significant number of tumours (ABCB1, BRCA1, CDKN2A, FOXC1, GSTP1, IGF2, PPP2R2B and PTEN) within the discovery cohort were tested for association with survival by a logrank test." (PMID 20338046, 2010). "A shared function of the neighbouring genes CDKN2A/2B and MTAP is the regulation of cell proliferation/tumor suppression." (PMID 19214202, 2009). "A recent study reported promoter methylation profiles of hMLH1, MGMT and CDKN2A in 51 cases of HNSCCs using MSP and demonstrated that tumours with two or more methylated genes had improved DFS at 2 years." (PMID 18594522, 2008). "The human chromosome 9p21 locus has three different genes that have tumor suppressor functions, namely cyclin-dependent kinase inhibitor 2A (CDKN2A): p16INK4a and p14ARF (INK4a/ARF) and CDKN2B: p15INK4b, respectively." (PMID 21892281, 2008). "Performing QMSP with a panel of three genes (CDKN2A, CCNA1 and DCC), we found 64% of HNSCC tumours were hypermethylation informative." (PMID 18594522, 2008). "The 9p21.1 locus contains CDKN2A and the 18q21.1 contains DCC, both are well known tumor suppressors." (PMID 18549475, 2008). "To validate our experimental conditions we next measured in Akata cells the expression of cellular genes known to be reactivated by Zebularine in other tumor cell lines including CDKN1A, CDKN1B and CDKN2A genes." (PMID 17214905, 2007). "The frequency of homozygous deletions of CDKN2A detected by MLPA in ESFT cell lines (44%) and primary tumours (10%) is consistent with the literature using more established methods including Southern blot, PCR, and fluorescent in situ hybridisation." (PMID 17533400, 2007). "Hemizygous deletion of the region harbouring the CDKN2A and CDKN2B loci was identified in two tumours by means of fluorescent in situ hybridisation and MTAP was present by immunostaining in all but one tumour analysed." (PMID 15305192, 2004). "These tumours were also examined for MDM2 and P63 amplification, and for expression of p16INK4a/CDKN2a, cyclin E, p27Kipland Cox2." (PMID 11531258, 2001). "As CDKN2A null tumours lacked this ability, they had highly desaturated TAGs with shorter fatty acid tails." (PMID 40136651, 2025). "Notably, cyclin-dependent kinase inhibitor 2A (CDKN2A) and L1 cell adhesion molecule (L1CAM) hypermethylation correlates with tumor progression and invasiveness." (PMID 40557320, 2025). "NGS analysis did not detect PTEN or CDKN2A edits in any of these six masses harvested at euthanasia, likely due to the very small percentage and peripheral localization of viable tumor samples as observed by IHC staining." (PMID 39780710, 2025).
tumor (continued). "For instance, the loss of an m6A site can directly compromise the stability of crucial tumor suppressor transcripts like CDKN2A and BRCA2, thereby fueling oncogenic processes without changing the protein’s coding sequence." (PMID 41011238, 2025). "The results showed that patients with a high proportion of HIP1R+, CDKN2A+, and IDHR132H+ tumor cells had a significantly better prognosis than those with a low proportion of positive tumor cells, while a high proportion of EGFR+ tumor cells was associated with a poor prognosis." (PMID 40264576, 2025). "We established NTT tumours and RTT tumours of the YUMM1.7 mouse melanoma model (BrafV600E, Pten–/–Cdkn2a–/–) that express the model antigen ovalbumin (OVA) in Rag2–/– mice and performed ACT by intravenously injecting activated tumour antigen-specific CD8+ T cells (OT-1Luc)." (PMID 39604727, 2025). "Tumor analysis with ddPCR for somatic CNV did not reveal LOH of the CDKN2A locus at the tumor level." (PMID 40813536, 2025). "The classical subtype is defined by epidermal growth factor receptor (EGFR) amplification, loss of PTEN, and mutations in cyclin-dependent kinase inhibitor 2A (CDKN2A), all of which contribute to aggressive tumor behavior and a negative prognosis." (PMID 40075663, 2025). "Notably, the deletion of CDKN2A is commonly observed in MPNST cases, promoting the tumor's premalignant characteristics." (PMID 40182390, 2025). "This vulnerability was recapitulated in vivo through mouse models that showed that GPX4 inhibition led to prolonged survival in CDKN2A null, but not CDKN2A WT GBM tumours." (PMID 40136651, 2025). "This signature not only effectively stratifies patient risk but also delineates specific molecular pathways, such as those involving SELENOP, CDKN2A, and PGR, through which the diabetic milieu may drive tumor aggressiveness." (PMID 41244925, 2025). "While conventional cancer driver genes of sporadic PC were not involved in our case, deletions were identified in the tumor suppressor genes CDKN2A, LATS1, ARID1A, and ARID1B." (PMID 40362680, 2025). "Moreover, CDKN2A, which was closely correlated to pan-cancer prognosis, was especially analysed including TIME alteration, genomic heterogeneity and tumour stemness." (PMID 40560740, 2025). "MiR-hsa-125b-5p affects cell proliferation, migration, and invasion by targeting multiple tumor suppressor genes such as CD147 and TPD52, and it participates in cancer progression by targeting STAT3, BMPR1B, VEGFA, SphK1, CDKN2A, and Sema4D." (PMID 41361055, 2025). "Germline variants not previously reported in WT were: CDKN2A R24Q (XJN) and STK11 L245F (QXN), both of which became homozygous in the tumor through LOH." (PMID 40340749, 2025). "In G4IDHwt, CDKN2A gene status exerted a negative effect on tumor necrosis and microvascular density." (PMID 40002588, 2025). "This is not due to any of our model’s particularities, as Cdkn2a was rapidly altered/lost in TCs following primary tumor transplantation in nude mice." (PMID 41223283, 2025). "Deletions in CDKN2A (cyclin-dependent kinase inhibitor 2A) impair the cell cycle checkpoint, whereas aberrant activation of stem cell markers such as SRY-Box transcription factor 2 (SOX2) supports tumor cell self-renewal and invasion." (PMID 40628732, 2025).
tumor (continued). "Despite these insights, none of the 16 studies included molecular or epigenetic tumor profiling, such as TERT promoter mutations, CDKN2A/B deletions, or methylation subclasses, which are increasingly shown to correlate with prognosis and RT responsiveness." (PMID 40940847, 2025). "This primed CDKN2A null GBMs for ferroptosis and inhibition of GPX4 through RSL3 led to significant cell death in CDKN2A null but not CDKN2A WT tumours." (PMID 40136651, 2025). "As expected, adjacent normal liver biopsies did not harbor PTEN or CDKN2A gene edits, confirming the specificity of the genetic alterations to the tumor cells subjected to in vitro CRISPR/Cas9." (PMID 39780710, 2025). "Examination of H&E-stained sections showed that all tumor histologies resembled those previously reported, thus indicating that Cdkn2a inactivation also did not significantly affect the microscopic appearance of tumors." (PMID 41008846, 2025). "Moreover, the dysregulation of cell-cycle-regulated genes (PLK1, CCNB1, CDKN2A, CCNE2, E2F1, and E2F2) by miR-5100 consistently resulted in upregulation in tumor tissues." (PMID 39590378, 2024). "CDKN2A could serve as a biomarker for ICI sensitivity, endorsing the utilization of ICIs to enhance anti-tumor immune responses in patients with inactive CDKN2A." (PMID 38534309, 2024). "We did not observe a significant difference in tumour purity based on CDKN2A/B HD status (CATNON: p = 0.46, TCGA: p = 0.39)." (PMID 39382765, 2024). "Firstly, using the relevant data of IHC in the HPA database, the key genes CDKN2A, MSLN, and CKMT2 were compared at the protein level, and it was found that CDKN2A and MSLN were significantly highly expressed in the tumor tissues (p < 0.001; p < 0.05), which was consistent with our prediction." (PMID 39519383, 2024). "The tumor samples from HPV-positive patients showed a higher level of CDKN2A as compared with those with negative HPV status (7.7355 (6.1427–10.592) vs. 3.0240 (1.7708–4.0156); p = 0.0034)." (PMID 39590385, 2024). "Both in Bueno and TCGA cohorts, we observed that several tumours with high CDKN2A transcripts did not display any defect or low expression of RB1." (PMID 36453028, 2024). "Moreover, the unexpected downregulation of CDKN2A despite predictions of upregulation based on bioinformatics models might be attributed to its role in a different cellular context, such as its known tumor-suppressive function in cancer (Morigi, Perico & Benigni, 2018)." (PMID 39494277, 2024). "Interestingly, the tumour with the highest degree of CDK4 phosphorylation (E3, a patient who died 2 months after diagnosis) presented also an elevated CDKN2A mRNA expression, but its p16 staining was weak." (PMID 36453028, 2024). "Nevertheless, seven tumours were observed with defects or very low expression of both RB1 and CDKN2A, showing that the coexistence of both defects in MPM_36 cells might not result from a culture artefact." (PMID 36453028, 2024). "Although known as a cuproptosis inhibitor through CRISPR-Cas9 screening, the role of cyclin-dependent kinase inhibitor 2A (CDKN2A) in cuproptosis resistance and its connection to tumor development remains unclear." (PMID 38888512, 2024).
tumor (continued). "In the sphere formation assay, si-CDKN2A, si-NC, Vector, and CDKN2A cells were cultured in non-adherent conditions to promote the formation of tumor spheres." (PMID 38438773, 2024). "Further molecular interrogation of the tumor revealed it was negative for BRAFV600E mutation and positive for CDKN2A homozygous deletion." (PMID 39108689, 2024). "In most tumor types, the frequency of CDKN2A-DEL was greater than that of CDKN2A MUT." (PMID 38822443, 2024). "Specifically, twelve marker genes, including DSC2 and CDKN2A, were identified for TNBC tumor cells." (PMID 38539508, 2024). "Our analysis showed no statistical differences in the expression levels of CDKN2A and Ki-67 proteins in the tumor samples as compared to the surgical margin samples." (PMID 39590385, 2024). "CDKN2A and KRAS occur in the early stages of tumor development." (PMID 39040449, 2024). "Despite these differences, all six tumor areas shared copy number changes including a hailstorm on chromosome 22 with congruent CNTs, a CNT upstream of TERT and focal deletion of CDKN2A/B, supporting their common clonal ancestry." (PMID 39034322, 2024). "CDKN2A HD was absent in tumor areas where MTAP expression was preserved and CDKN2A HD was observed in tumor cells with MTAP loss." (PMID 38109891, 2024). "A previous meta-analysis pooled dichotomous data on CDKN2A/B deletions (tumor recurrence/death: yes or no)." (PMID 39593128, 2024). "In other words, analogous to CDKN2A/B HD, CDK4 and MDM2 co-amplification might accelerate tumor progression and may induce a malignant phenotype." (PMID 38012788, 2023). "It is worth mentioning that the CD8 T cell was not the only affected immune component with the CDKN2A alteration in our study but also other chemokines and chemokine receptors, which modulate the state of tumor progression, were also affected." (PMID 37626750, 2023). "Neither PRC2 disruption nor CDKN2A expression, however, was sufficient for sustained suppression of tumor growth." (PMID 36635771, 2023). "Few tumors without CDKN2A HD remained underscored even after unblinded consensus analysis, due to low tumor cellularity." (PMID 37138345, 2023). "Although the original tumor grading was not based on the CDKN2A status in our discovery cohort, CDKN2A was homozygously deleted and dramatically downregulated in four progressed grade 4 tumors." (PMID 37932833, 2023). "Detection of homozygous CDKN2A/B deletion leads to classification as a grade 4 tumour, even in the absence of the classic grade 4 histologic features of necrosis or microvascular proliferation." (PMID 37316586, 2023).